TUSC3 (tumor suppressor candidate 3)
Diseases named in the same sentence as TUSC3 in open-access papers (continued):
Sharing a sentence is not in itself a finding about the gene and the disease.
prostate carcinoma (7 papers, 2016 to 2022). A carcinoma that arises from epithelial cells of the prostate gland. "For example, loss of TUSC3 expression in prostate cancer cells results in increased proliferation, migration, and invasion by affecting ER stress via Akt signaling." (PMID 36274132, 2022). "The associations of HFE rs9393682 and TUSC3 rs1378033 with prostate cancer progression was replicated across both cohorts, which would reduce false-positive findings in this study." (PMID 29088772, 2017). "The associations of HFE rs9393682 and TUSC3 rs1378033 with disease progression were replicated across both stages of the study for localized and advanced prostate cancer, respectively." (PMID 29088772, 2017). "According to multivariate analyses adjusted for known predictors, HFE rs9393682 was found to be associated with disease progression for localized prostate cancer, and TUSC3 rs1378033 was associated with progression for advanced prostate cancer in both cohorts." (PMID 29088772, 2017). "Peter Horak found that TUSC3 loss increased N‐glycosylation of cell surface proteins and alleviates endoplasmic reticulum stress in prostate cancer cells." (PMID 28272772, 2017). "Loss of TUSC3 has been proposed to facilitate prostate cancer progression by increasing protein glycosylation, alleviating unfolded protein response and ER stress, and promoting Akt survival signaling." (PMID 29088772, 2017). "Loss of TUSC3 expression in prostate cancer cell lines leads to increased proliferation, migration and invasion as well as accelerated xenograft growth." (PMID 28272772, 2017). "In addition, TUSC3 expression was down-regulated in late stage cancers, and low TUSC3 expression was significantly associated with shorter TTP in prostate cancer, as well as decreased survival in several TCGA cancer sets." (PMID 29088772, 2017). "Taken together, these observations indicate that 1,25-VD can stimulate TUSC3 expression, and down-regulation of TUSC3 in late stages of cancer may increase the risk of prostate cancer progression." (PMID 29088772, 2017). "However, in another paper concerning prostate cancer, it was found that decreased TUSC3 is associated with increased N-glycosylation." (PMID 26871953, 2016). "In prostate cancer cell model, TUSC3 loss under serum deprivation promotes Akt activity." (PMID 26871953, 2016). "To better understand the roles of HFE and TUSC3 in prostate cancer, we used small interfering RNAs (siRNAs) to silence their expression in PC-3 cells, and evaluate the consequences of loss of HFE or TUSC3 function on cell proliferation and migration." (PMID 29088772, 2017). "In contrast, vitamin D treatment induced TUSC3 expression, and silencing TUSC3 promoted prostate cancer cell growth and migration." (PMID 29088772, 2017). "This study shows that HFE rs9393682 and TUSC3 rs1378033 influence TTP in patients with prostate cancer." (PMID 29088772, 2017). "We then assessed HFE and TUSC3 expression using a prostate cancer complementary DNA array containing 39 tissue samples." (PMID 29088772, 2017). "The prognostic values of HFE and TUSC3 on prostate cancer progression were further evaluated using a publicly available prostate cancer microarray dataset." (PMID 29088772, 2017). "Silencing TUSC3 promotes prostate cancer cell proliferation and migration, and its expression is decreased in advanced stage cancer tissues, as well as in patients with poor prognosis." (PMID 29088772, 2017). "This study identifies common variants in VDR-binding sites as prognostic markers of prostate cancer progression and HFE and TUSC3 as plausible susceptibility genes." (PMID 29088772, 2017). "In addition, knockdown HFE and TUSC3 expression significantly influenced prostate cancer cell proliferation and migration." (PMID 29088772, 2017). "Our data also showed that silencing TUSC3 expression could increase prostate cancer cell proliferation and migration." (PMID 29088772, 2017).
prostate carcinoma (continued). "Reduction of TUSC3 gene expression in prostate cancer may be because of its methylation 10, and some of these methylation changes may initiate in subpopulations of normal cells as a function of aeging and progressively increase during carcinogenesis." (PMID 28272772, 2017). "Interestingly, according to the information from the previous publications, TUSC3 exerts its regulating effects on UPR, and TUSC3-deficiency specifically activates ATF6-branch mediated UPR to promote cancer development and metastasis in prostate cancer and non-small cell lung cancer." (PMID 34381729, 2021). "The expression of two genes near these VDRE SNPs, HFE and TUSC3, can be regulated by 1,25-VD, suggesting that HFE and TUSC3 might be potential vitamin D target genes and thus contribute to prostate cancer progression." (PMID 29088772, 2017). "In prostate cancer, though there appears a trend toward poorer outcome with decreased TUSC3 mRNA expression, the difference is not statistically significant." (PMID 26871953, 2016). "In addition, previous research has demonstrated that suppressing TUSC3-dependent AKT signaling pathway may affect the progression of melanoma cells, prostate cancer cells, and cervical squamous cell carcinoma cells." (PMID 36274132, 2022). "The effects of 1,25-VD on the mRNA expression levels of HIST1H1C, HFE, SGCZ, TUSC3, and CYP24A1 (cytochrome P450 family 24 subfamily A member 1), a well-known 1,25-VD target gene, were examined using quantitative real-time polymerase chain reaction (qRT-PCR) in PC-3 human prostate cancer cells." (PMID 29088772, 2017).
Intellectual disability (5 papers, 2011 to 2021). "Few families around the world were reported to have mutations in the TUSC3 gene resulting in intellectual disability." (PMID 34646667, 2021). "Of these, particular genes of interest include ATG7, which has been associated with frontotemporal dementia; TUSC3, a gene associated with intellectual disability; and PARK2, a gene associated with Parkinson’s disease." (PMID 25887117, 2015). "TUSC3 variants are known to cause Mental Retardation, Autosomal Recessive 7 (MRT7) [MIM 611093]." (PMID 30500859, 2018). "One study suggests the involvement of N-glycosylation in higher brain functions, while another postulates disturbed magnesium levels due to TUSC3 impairment may play a role in the pathogenesis of intellectual disability." (PMID 30500859, 2018).
gastric cancer (4 papers, 2021 to 2024). A primary or metastatic malignant neoplasm involving the stomach. "lncRNA MIR503HG and a signalling cascade composed of its downstream targets miR‐224‐5p and tumour suppressor candidate 3 (TUSC3) suppress cancer development by modulating ATF6 in gastric cancer." (PMID 39072992, 2024).
hepatocellular carcinoma (4 papers, 2017 to 2024). A malignant tumor that arises from hepatocytes. "Down-regulation of TUSC3 promotes EMT progression by activating AKT signaling via targeting LIPC in HCC, which is probably the possible mechanism driving TUSC3-deficient hepatocellular carcinoma cells toward a malignant phenotype." (PMID 36274132, 2022). "TUSC3 was aberrantly decreased in hepatocellular carcinoma tissues compared to the matched adjacent normal tissues, which resulted in bigger size of tumor (P = 0.001), worse differentiation (P = 0.006) and an advanced BCLC stage." (PMID 36274132, 2022). "Down-regulation of TUSC3 led to the enhanced proliferation and migration of hepatocellular carcinoma cells in vivo and vitro, whereas the opposite effect could be observed in the TUSC3-overexpression group." (PMID 36274132, 2022).
lung carcinoma (4 papers, 2018 to 2021). "Moreover, the expression of TUSC3 gene was associated with lymph node metastasis and consistently suppressed in advanced lung cancers including small cell lung cancer and lung adenocarcinoma, a subtype of NSCLC30,52." (PMID 30504895, 2018). "However, genetic deletion and/or epigenetic modification such as induction of miR-224/520c in advanced lung cancers is responsible for TUSC3 deficiency." (PMID 30504895, 2018). "It is reported that DGCR5 suppresses lung cancer cell proliferation, migration, and invasion by targeting miR-1180 and by interacting with miR-873-5p to regulate the tumor suppressor candidate 3 (TUSC3)." (PMID 34322486, 2021). "For figuring out the roles of miR‐873‐5p and TUSC3 in lung cancer progression, the expression levels of miR‐873‐5p and TUSC3 in the neoplastic and non‐neoplastic tissues from patients with LC were detected by qRT‐PCR." (PMID 29790668, 2018). "An ER-membrane protein, TUSC3 functions in cancer pathogenesis by context dependent manner, but remains controversial in lung cancer." (PMID 30504895, 2018). "Subsequent cell biological assays showed TUSC3 inhibited lung cancer cell proliferation and induced cell death." (PMID 30504895, 2018). "First, we observed that TUSC3 expression was frequently suppressed in the metastasized lung cancer patient samples compared to primary lung cancer, possibly mediated by the increased expression of miR-224 and/or miR-520c." (PMID 30504895, 2018). "To analyze TUSC3 expression in lung cancer, we employed 20 normal, 14 primary and 21 lymph node metastasized lung tumor tissues." (PMID 30504895, 2018). "Furthermore, IHC for co-expression analysis using anti-TUSC3 and anti-ATF6α antibodies in primary and metastasized lung cancer patient samples showed that enhanced and/or nuclear localized ATF6α protein was highly inversely correlated with TUSC3 expression." (PMID 30504895, 2018). "However, the role of TUSC3 still remains controversial in lung cancer and context-dependent in several cancers." (PMID 30504895, 2018). "Moreover, co-expression analyses using IHC assay followed by in situ hybridized samples revealed that there was an inverse correlation between miR-224/-520c and TUSC3 expression in lung cancer patient samples." (PMID 30504895, 2018). "Our current observation could provide important insight to understanding the controversial roles of TUSC3 in lung cancer metastasis and the specific roles of UPR and HRD1 regulation in TUSC3-deficient lung cancer, as an anti-cancer therapeutic strategy against NSCLC." (PMID 30504895, 2018). "Another study showed that TUSC3 expression was downregulated in small cell lung cancer, and TUCS3 may become a predictor of lymph node metastasis in lung cancer patients." (PMID 34733314, 2021). "Utilizing TUSC3KO and TUSC3/HRD1 DKO cells, we found that ATF6α pathway, but not IRE1α and PERK pathways was selectively enhanced in TUSC3 deficient cells, possibly mediated the function of TUSC3 deficiency in lung cancer metastasis." (PMID 30504895, 2018).
lung carcinoma (continued). "To date, none of the plausible mechanisms investigated TUSC3-dependent regulation of lung cancer progression and metastasis. miRNAs, the most abundant endogenous small non-coding RNA, are often dysregulated in most cancers, which consequently controls key regulators in tumorigenesis." (PMID 30504895, 2018).
breast tumour (3 papers, 2008 to 2017). "We found that the protein levels of TUSC3 are decreased in breast tumour tissues as compared to surrounding normal tissues." (PMID 28288641, 2017). "Two cell lines have deletions that solely affect TUSC3 and result in decreased expression and expression was lost or decreased in 31% of primary breast tumours." (PMID 18840272, 2008). "Anecdotally, TUSC3 also showed decreased expression in a panel of 61 primary breast tumours." (PMID 18840272, 2008). "For example, a low rate of promoter methylation was observed for the TUSC3 (9/105 samples), MGMT (8/105 samples) and CDKN2B (2/105 samples) genes in breast tumors." (PMID 23472065, 2013).
thyroid cancer (3 papers, 2021 to 2022). "Furthermore, as a sponge of miR-515-5p, ZFPM2-AS1 decreased the ability of miR-515-5p to inhibit TUSC3 expression by pull-down, luciferase reporter and gain-and-loss assays, thereby promoting malignant progression of thyroid cancer." (PMID 33976749, 2021). "Furthemore, a recent study indicated that ZFPM2-AS1 promote thyroid cancer progression via sponging miR-515-5p to modulate TUSC3 expression." (PMID 35416526, 2022). "Mechanistically, ZFPM2-AS1 was transcriptionally regulated by STAT1 and bound to miR-515-5p through competitive competition with TUSC3 in thyroid cancer cells." (PMID 33976749, 2021). "TUSC3 knockdown prominently suppressed proliferative and invasive capacities of thyroid cancer cells." (PMID 33976749, 2021). "miR-515-5p distinctly inhibited TUSC3 expression in thyroid cancer cells, which was reversed after co-transfection of pcDNA3.1-ZFPM2-AS1." (PMID 33976749, 2021). "In addition, ZFPM2-AS1 promotes the growth, migration, and invasion of thyroid cancer cells through the miR-515-5p/TUSC3 axis." (PMID 35416526, 2022). "We found that TUSC3 was a target of miR-515-5p, which was over-expressed in thyroid cancer." (PMID 33976749, 2021). "Furthermore, miR-515-5p-induced reduction in clonal formation and proliferation was improved after transfection with TUSC3 overexpression in thyroid cancer cells." (PMID 33976749, 2021). "Collectively, miR-515-5p may suppress proliferation and invasion for thyroid cancer cells by inhibition of TUSC3 expression." (PMID 33976749, 2021). "Mechanistically, ZFPM2-AS1 transcriptionally regulated by STAT1, could bind miR-515-5p through competitively competing with TUSC3 in thyroid cancer cells." (PMID 33976749, 2021). "Thus, ZFPM2-AS1 bound to miR-515-5p via competitive competition with TUSC3 in thyroid cancer cells." (PMID 33976749, 2021). "Collectively, miR-515-5p could mediate TUSC3 expression in thyroid cancer." (PMID 33976749, 2021).
Autosomal Recessive Mental Retardation (2 papers, 2010 to 2017). "In a recent study, a homozygous deletion in the TUSC3 locus was shown to be associated with a form of Autosomal Recessive Mental Retardation." (PMID 20482829, 2010). "Defects in the TUSC3 gene have been identified in individuals with non‐syndromic autosomal recessive intellectual disability in different nations." (PMID 28272772, 2017). "Known to be related to autosomal recessive mental retardation for several years, TUSC3 has only recently been identified as a potential tumour suppressor gene." (PMID 28272772, 2017).
cervical cancer (2 papers, 2022 to 2024). A primary or metastatic malignant neoplasm involving the cervix. "Decreased TUSC3 expression levels were significantly associated with proliferation and an aggressive phenotype of cervical cancer cells both in vitro and in vivo." (PMID 35137520, 2022). "The association of TUSC3 with patient prognosis was analysed, as well as its cellular and molecular function in cervical cancer cell migration and invasion." (PMID 35137520, 2022). "We revealed that TUSC3 may modulate the AKT and regulate MMP9 to enhance cervical cancer cells invasion." (PMID 35137520, 2022).
cervical squamous cell carcinoma (2 papers, 2022). A squamous cell carcinoma arising from the cervical epithelium. "The present study aimed to assess the cellular and molecular function of TUSC3 in patients with cervical squamous cell carcinoma (CSCC)." (PMID 35137520, 2022).
glioma (2 papers, 2012 to 2022). A benign or malignant brain and spinal cord tumor that arises from glial cells (astrocytes, oligodendrocytes, ependymal cells). "Taken together, these data suggest that transcriptional changes in healthy aging tissue, such as TUSC3 silencing, may contribute to the more severe form of glioma in older patients." (PMID 23046790, 2012).
head and neck cancer (2 papers, 2020 to 2021). A primary or metastatic malignant neoplasm affecting the head and neck. "While the direction of this effect is inconsistent with its putative role as a tumor suppressor, up-regulation of TUSC3 and possible oncogenic roles for this gene have been reported in cancers including non-small cell lung cancer, colorectal, thyroid, and head and neck cancers." (PMID 32894098, 2020).
lung adenocarcinoma (2 papers, 2016 to 2018). A carcinoma that arises from the lung and is characterized by the presence of malignant glandular epithelial cells. "Additionally, ADAMTS8, DMBT1 and DOCK8 were down-regulated in adenocarcinoma and STMN2 and TUSC3 were up-regulated in lung adenocarcinoma (all P < 0.01)." (PMID 27980454, 2016). "For the other five genes (STMN2, SPINK6, TUSC3, LOC100128054, and C8orf22), we found that STMN2, TUSC3 and C8orf22 were upregulated in squamous cell carcinoma and that STMN2 and USC3 were upregulated in lung adenocarcinoma." (PMID 27980454, 2016). "We found that RSPO3, ADAMTS8, DMBT1, DOCK8, STMN2, SPINK6 and TUSC3 were the co-genes of HOXA11-AS in lung adenocarcinoma whereas RSPO3, ADAMTS8, DMBT1, DOCK8, STMN2, SPINK6, TUSC3 and C8orf22 were the co-genes of HOXA11-AS in squamous cell carcinoma." (PMID 27980454, 2016).
Lymph node metastasis (2 papers, 2017 to 2018). "Additionally, a marked decrease of TUSC3 expressions in patients with Lymph node metastasis positive (LNM+) was identified compared with patients with Lymph node metastasis negative (LNM−)." (PMID 28272772, 2017). "Our results indicated that TUSC3 expressions may be a useful predictor of lymph node metastasis in SCLC cancer patients (Data not shown)." (PMID 28272772, 2017).
metastatic prostate carcinoma (2 papers, 2010 to 2017). A carcinoma that arises from the prostate gland and has spread to other anatomic sites. "TUSC3 was identified as a potential tumor suppressor gene on chromosome 8p22, a common homozygously deleted region of the metastatic prostate cancer." (PMID 29088772, 2017). "TUSC3 (also N33) is an 11 exon gene spanning approximately 224 kb that was first cloned from a homozygous deletion found in metastatic prostate carcinoma, suggesting a tumour suppressor role for this gene." (PMID 20482829, 2010).
non-small cell lung carcinoma (2 papers, 2020 to 2021). A group of at least three distinct histological types of lung cancer, including non-small cell squamous cell carcinoma, adenocarcinoma, and large cell carcinoma. "Previous data suggested that ER stress mediated UPR contributes to cancer metastasis, and TUSC3-deficiency enhanced UPR to promote metastatic potential of non-small cell lung cancer (NSCLC), which encouraged us to investigate whether LncRNA MIR503HG inhibited GC metastasis in a UPR-dependent manner." (PMID 34381729, 2021).
oral squamous cell carcinoma (2 papers, 2017 to 2024). "Ribeiro 32 found that loss of TUSC3 gene may serve as a good indicator of malignancy in oral squamous cell carcinoma." (PMID 28272772, 2017).